CD40 (CD40 molecule)
Diseases named in the same sentence as CD40 in open-access papers (continued):
Sharing a sentence is not in itself a finding about the gene and the disease.
atherosclerosis (continued). "In the 1990s, it was discovered that inhibition of CD40 signaling by blocking CD40L limits the evolution of established atherosclerosis in mice." (PMID 27146510, 2016). "Evidence is presented that the activation of CD40 on macrophages accelerates atherosclerosis, accelerates neointima formation, and attenuates arteriogenesis." (PMID 27146510, 2016). "CD40 serves as a link between inflammation, atherosclerosis and thrombosis; our functional tests have successfully identified miR-145 as being involved in the regulation of CD40 because over-expression of miR-145 significantly inhibits the expression of CD40." (PMID 27731400, 2016). "We will discuss the function of CD40 on the macrophage and its (proposed) role in the reduction of atherosclerosis, the reduction of neointima formation, and the stimulation of arteriogenesis." (PMID 27146510, 2016). "Recent work has revealed an essential involvement of sCD40L and its receptor CD40 in atherosclerosis and restenosis." (PMID 23785403, 2013). "The CD40/CD40L system has been implicated in several cardiovascular diseases, such as atherosclerosis, ischemic heart disease, and stroke." (PMID 21876738, 2011). "As it is highly expressed in atheromatous plaques also, inhibitors of CD40/CD40 ligand pathway can be novel molecules for delaying progression of atherosclerosis." (PMID 21572750, 2010). "Similarly, in atherosclerosis, enhanced M1 marker expression (e.g., CD40/CD86) strengthens adaptive immunity." (PMID 41011253, 2025). "In addition, crosstalk between CD4+ T-lymphocytes and B-lymphocytes via MHC II and CD40 molecules increases development of atherosclerosis." (PMID 40498464, 2025). "Its interaction with CD40 is critical in the context of atherosclerosis and restenosis." (PMID 40598260, 2025). "Furthermore, we took advantage of the atherosclerosis-prone ApoE-/- mouse model to investigate the role of CD40 signaling on atherosclerosis (ATS) progression." (PMID 39767610, 2024). "However, there is limited evidence to suggest that DCs expressing CD40/CD40L are related to atherosclerosis." (PMID 38579073, 2024). "In particular, NP31 was found not only to alter the biodistribution profile of a streptavidin scaffold but also to significantly increase the accumulation of the carrier in aged apolipoprotein e (ApoE) mice with atherosclerosis lesions in a CD40-dependent manner." (PMID 35955688, 2022). "The role of CD40 in atherosclerosis has been extensively studied by our group and others." (PMID 35336782, 2022). "Therefore, visualizing CD40 by PET in atherosclerosis has the potential to predict plaque vulnerability." (PMID 35336782, 2022). "Although Tregs are of major importance during atherogenesis, the reduction in Tregs that we observed in our T cell-deficient CD40L and DC-deficient CD40 mice did not result in aggravated atherosclerosis." (PMID 34145241, 2021). "The study also demonstrated that hsa_circ_0004104 may contribute to the pathogenesis of CAD by upregulating of atherosclerosis-susceptible genes, such as IDO1, MMP8, CD40, and downregulating of anti-atherosclerosis genes, such as ApoA I, RNASE1." (PMID 33421993, 2021). "Indeed, large amounts of research have revealed the substantial role of CD40 in the process of sepsis, atherosclerosis, ischemic stroke, and Alzheimer's disease." (PMID 33005203, 2020). "The in vivo study demonstrated that TRAF6-rHDL NPs could reduce the expression of CD40 and integrin in classical monocytes, thereby reducing monocyte recruitment and impeding the initiation of atherosclerosis." (PMID 31984429, 2020). "CD40/CD40L signalling pair plays a central role in inducing adaptive immunity in atherosclerosis." (PMID 29364567, 2018).
atherosclerosis (continued). "The expression of CD40L and its classical ligand CD40 on many of the participating cells, including various leukocyte subpopulations, ECs, and SMCs, has led to the hypothesis that the CD40L/CD40 dyad may contribute to atherosclerosis." (PMID 28676852, 2017). "CD40L and CD40 were identified in human atherosclerotic lesions at every developmental stage, and CD40 expression in lesional macrophages and SMCs correlates with the stage of atherosclerosis." (PMID 28676852, 2017). "The involvement of CD40 signaling in atherosclerosis has been firmly established." (PMID 27146510, 2016). "A previous study has shown that the activation of CD40 inhibits endothelial cell migration by increasing ROS production, and another study has provided evidence that ROS mediate a key initiating step in the development of atherosclerosis." (PMID 26799794, 2016). "Though never proven, one could imagine that the plaque environment alters CD40 signaling, and thus affects atherosclerosis." (PMID 27146510, 2016). "There is convincing evidence, suggesting a large role of CD40 on macrophages in atherosclerosis." (PMID 27146510, 2016). "Specific inhibition of macrophage CD40 might act as a “double-edged sword” by inhibiting atherosclerosis and stimulating arteriogenesis, resulting in a reduced ischemic burden without interfering in adaptive immunity." (PMID 27146510, 2016). "CD40 and CD40 ligand activation are known to be important inflammatory signals in atherosclerosis." (PMID 26095681, 2015). "CD40 plays a key role in the pathogenesis of atherosclerosis and diabetic retinopathy." (PMID 26710229, 2015). "Since the CD40/CD154 axis participates in the genesis of inflammatory conditions including atherosclerosis and neuroinflammation, manipulation of this system by immunomodulatory agents such as atorvastatin would provide a useful means to shift the T cell response towards a regulatory phenotype." (PMID 25013913, 2014). "Thus, our studies suggest that iron could be a potential environmental factor regulating atherosclerosis‐associated cellular senescence, and this is achieved by modulating PCBP2‐dependent p16INK4a and CD40 expression." (PMID 41216990, 2025). "The exact role of CD40 signaling on B cells in atherosclerosis remains unclear, but it is possible that oxLDL-specific IgM antibodies from B cells may be relevant to the development of atherosclerosis." (PMID 38579073, 2024). "The results confirmed that saponin regulated the CD40-related signaling pathway by affecting ubiquitination degradation, which in turn inhibited platelet activation, contributing to anti-inflammatory and antithrombotic effects during atherosclerosis development." (PMID 33584257, 2020). "Finally, this pathway may be functional in other diseases driven by CD40 such as inflammatory bowel disease, atherosclerosis and lupus nephritis." (PMID 31921199, 2019). "The finding that CD40 deficiency did not protect from atherosclerosis in at least one of these two studies has raised the possibility that CD40 may not be an exclusive receptor for CD40L." (PMID 28676852, 2017). "However, further research focusing on the role of miR-145/CD40 pathway in inflammation or CVD/atherosclerosis model is still necessary to verify our findings and other pathogenic factors of cardiovascular diseases should also be considered in subsequent studies." (PMID 27731400, 2016). "Targeting miR-145/CD40 might be a useful strategy for treating atherosclerosis." (PMID 27731400, 2016). "While the studies presented herein were done in vitro, our findings raise the possibility that CD40-mediated CX3CL1 upregulation in endothelial cells may be relevant in vivo by promoting monocyte recruitment during atherosclerosis or arterial injury-driven neointima formation." (PMID 26710229, 2015).
atherosclerosis (continued). "Comparable results were seen upon deficiency of Cd40-Traf2/3/5 signalling in Apoe−/− mice, which did not affect atherosclerosis despite an increase in both atheroprogressive effector memory T-cells and atheroprotective Treg cells in blood and secondary lymphoid organs." (PMID 24498325, 2014). "In addition to cytokine and chemokines genes the “Atherosclerosis Signalling” and “Communication between Innate and Adaptive Immune cells” pathways had CD40, ICAM1, ORM1 and ORM2 as being significantly expressed within the pathways at 1 hour following LPS and Pam3CSK4 stimulation." (PMID 24842522, 2014). "The effects of CD40 and CD40L on atherosclerosis, specifically atherothrombosis, have been well studied." (PMID 38887301, 2024). "The interaction between CD40 and CD40 ligand (CD40L) a crucial co-stimulatory signal for activating adaptive immune cells, has a noteworthy role in atherosclerosis." (PMID 38579073, 2024). "Over the past 3 decades, numerous researches have highlighted the correlation between CD40/CD40L interactions and the occurrence and progression of atherosclerosis." (PMID 38579073, 2024). "High levels of cluster of differentiation 40 (CD40) and its corresponding ligand (CD40L), which influence EC activation and monocyte recruitment leading to the acceleration of atherosclerosis development, have been observed in diabetic patients." (PMID 37503820, 2023). "This led to T cell activation and CD40 suppression by STAT1 ODN, presenting a protective effect against atherosclerosis advancement." (PMID 36614305, 2023). "Small-molecule inhibitors that block the interaction between CD40 and TRAF6 (TRAF-STOPs) overcome the current limitations of long-term CD40 inhibition in atherosclerosis, which has the potential to become a future therapeutic for atherosclerosis." (PMID 36237831, 2022). "Both CD40 and CD40L are expressed in human atherosclerotic lesions, and showed increased expression when atherosclerosis progresses, with highest expression in vulnerable plaques." (PMID 35336782, 2022). "The CD40/CD40 ligand (CD40L) dyad plays a significant role in several immunogenic and inflammatory processes, including atherosclerosis." (PMID 35955688, 2022). "The interaction between CD40 and its corresponding ligand, CD40L, is known to induce platelet activation, thereby leading to inflammation and atherosclerosis." (PMID 32517700, 2020). "In summary, the current findings suggest that platelet CD40 and CD40L can serve as a key interface between inflammation, thrombosis, and atherosclerosis and are attractive potential therapeutic targets for cardiovascular disease." (PMID 33371312, 2020). "Additionally, CD40, F11R, TNRC18, and calcium/calmodulin-dependent protein kinase type II gamma (CAMK2G) were screened out and validated using enzyme-linked immunosorbent assay (ELISA) in an independent patient cohort and immunohistochemical (IHC) staining in an atherosclerosis mouse model." (PMID 32714363, 2020). "The dysfunction of the CD40/CD40L system has been reported to participate in the development and progression of atherosclerosis, sepsis, and other inflammatory diseases." (PMID 33005203, 2020). "Inflammatory cytokines and modified lipids were shown to increase expression of CD40 on ECs, explaining why CD40L-dependent activation of ECs is enhanced in the pro-inflammatory milieu of atherosclerosis." (PMID 28676852, 2017). "It has been challenging to specifically attribute platelet-expressed CD40 and CD40L to atherosclerosis due to the limited availability of conditional knockout models in the past." (PMID 28676852, 2017). "Like in atherosclerosis, TRAF6 seems to be the key regulator of CD40 signaling in neointima formation and arterial remodeling." (PMID 27146510, 2016).
atherosclerosis (continued). "CD40 and CD40 ligand (CD40L) have a critical role in the pathophysiology of atherosclerosis and atherothrombosis." (PMID 26289439, 2015). "CD40 and CX3CL1 have a well-established role in the pathogenesis of vascular inflammatory disorders such as atherosclerosis and neointima formation after arterial injury." (PMID 26710229, 2015). "This suggest that the treatments of G1 and PCA can effectively down-regulate the inflammatory markers (VCAM-1 and CD40) and up-regulate GPER-1 and CD31 to attenuate atherosclerosis for both short and long term." (PMID 25411835, 2014). "During the past decade, the cluster of differentiation 40 (CD40) and its ligand (CD40L), as important inflammatory regulators, have been found to play a role in atherosclerosis." (PMID 21792360, 2011). "Experimental studies have also shown that the inhibition of CD40/CD40L pathway not only decreases vascular inflammation and prevents the development of atherosclerosis, but also protects ischemic coronary artery in rabbits." (PMID 21792360, 2011). "Inflammation is an important determinant of progression of atherosclerosis and post-thrombotic syndrome which complicates deep vein thrombosis (DVT) through CD40/CD40 ligand pathway and P selectin." (PMID 21572750, 2010). "Here, currently available data are revieweddemonstrating that CD40- CD40L interactions are operational in two chronic inflammatory clinical conditions,namely, multiple sclerosis and atherosclerosis." (PMID 9814595, 1998). "The interaction between CD40 and CD40L, cytokines involved in the modulation of the immune response that belong to the TNF receptor and its ligand superfamily, has appeared to be correlated with the occurrence and progression of atherosclerosis." (PMID 40573228, 2025). "A comprehensive blockade of CD40L or CD40 signaling does not appear to be a viable long-term treatment for atherosclerosis, mainly because of the undesirable side effects of immunosuppression or the risk of thromboembolic events." (PMID 39899926, 2025). "Notably, platelet-derived CD40 and CD40L play pivotal roles in plaque thrombosis and atherosclerosis progression." (PMID 41268556, 2025). "Even though B-cells have been shown to play various roles in the development of atherosclerosis, both beneficial and detrimental, our data suggest that in arterial hypertension, blocking CD40 on B-cells or T-cells is not beneficial." (PMID 39899926, 2025). "While there are non-B cell effects of CD40 disruption on atherosclerosis, B cell specific effects support the detrimental role of B-2 activation in plaque formation." (PMID 36461105, 2022). "Previously work has shown that treatment of ApoE−/− mice with IgG from an atherosclerotic animal promotes atherosclerosis development and prevention of proper germinal center formation or function, either by blocking AID or CD40 signaling, has an atheroprotective effect." (PMID 36461105, 2022). "The co-stimulatory molecule CD40 and its ligand CD40L (CD154) have a central role in the regulation of the inflammatory response during the development of atherosclerosis by modulating the interaction between immune cells and between immune cells and non-immune cells." (PMID 32222950, 2021). "The possible mechanisms by which the CD40 and CD40L systems affected atherosclerosis might be correlated with the immune inflammatory reaction." (PMID 32714363, 2020). "Therefore, Seijkens and coworkers studied an rHDL NP-mediated approach to suppress atherosclerosis by only targeting the interaction between TRAF6 and CD40 using a small molecule inhibitor (687702)." (PMID 31984429, 2020). "Adoptive transfer of B cells deficient in either MHCII or co-stimulatory molecule CD40, molecules required for B and CD4 T cell interaction, into B cell-deficient μMT−/− ApoE−/− mice failed to increase atherosclerosis." (PMID 31998318, 2019).
atherosclerosis (continued). "Androgens increase the expression of CD40 (among other atherosclerosis related genes) in male but not female macrophages, with functional consequences." (PMID 27146510, 2016). "Unfortunately, a model detailing the effect on atherosclerosis by a specific deletion of CD40 on macrophages has not been published yet." (PMID 27146510, 2016). "Given the important roles of the CD40/CD40L axis in the inflammatory response and ROS production in oxidative stress during the pathological process of atherosclerosis, we explored the mechanisms by which resveratrol reduces CD40 expression and ROS generation induced by TNF-α." (PMID 26799794, 2016). "The role of CD40 and its ligand CD40L in atherosclerosis has been extensively studied." (PMID 24478772, 2014). "The pivotal role of CD40L/CD40 in the pathogenesis of atherosclerosis and restenosis is now widely accepted." (PMID 23785403, 2013). "This may be due to the role of CD40 in thrombosis and inflammation, while MGP gene might have a protective role in atherosclerosis." (PMID 22135769, 2011). "A cluster of differentiation 40 (CD40) and CD40 ligand (CD40L, costimulatory molecules that belong to the superfamily of tumor necrosis factor (TNF) proinflammatory chemokines are contributory to the burden of atherosclerosis, plaque stability, and prothrombotic effects." (PMID 40573228, 2025). "However, it’s essential to note that long-term direct suppression of CD40 or CD40L could potentially result in immunosuppression, emphasizing the critical role of the CD40-CD40L system in atherosclerosis." (PMID 38579073, 2024). "Furthermore miR-181a is involved in the pathogenesis of atherosclerosis as it targets c-FOS and OPN and reduces the immune-inflammatory response induced by oxidized LDL by decreasing the expression of cell surface proteins like CD40 or CD83 on dendritic cells." (PMID 36267276, 2022). "The lack of Ig isotype switching, characteristic of CD40(L) deficiency, was also observed in our T cell deficient CD40L mice where total IgG, as well as oxLDL specific IgG, had decreased thereby contributing to the observed decrease in atherosclerosis." (PMID 34145241, 2021). "Activation of CD40 by proinflammatory cytokines such as CD40L (CD154) has been shown to augment the expression of matrix metalloproteinases, procoagulant tissue factor, chemokines, and cytokines, which regulate various inflammatory responses in the process of atherosclerosis." (PMID 26799794, 2016). "Therefore, strategies designed to suppress CD40/CD40L expression may attenuate inflammation, which will eventually offer benefits during the progression of atherosclerosis." (PMID 26799794, 2016). "In another study, the lack of the TRAF2, TRAF3, and TRAF5 binding site on CD40 in MHCII+ cells did not interfere with neointima formation after arterial injury and atherosclerosis." (PMID 35252400, 2022). "Most immune cells in the circulation as well as immune and non-immune cells within the atherosclerotic plaque express CD40 and CD40L during the development of atherosclerosis." (PMID 36703734, 2022). "Although inhibition of the CD40-TRAF-2/3/5 axis did not impact atherosclerosis, a knockout of TRAF-5 that was not specific for the CD40-binding site exacerbated atherosclerosis in mice by promoting leukocyte accumulation and foam cell generation in the plaque." (PMID 28676852, 2017). "It is noteworthy to mention that a selective blocker of the interaction between CD40 and TRAF6 (“TRAF-STOPs”) that does not affect CD40-TRAF2/3/5 interactions and preserves CD40-mediated immunity reduces atherosclerosis, likely by impairing inflammatory leukocyte recruitment." (PMID 35252400, 2022). "Although blocking the relationship between CD40 and CD40L is a possible treatment for atherosclerosis, blocking CD40L may not be a therapeutically feasible option because long-term blockade impairs the immune response throughout the body." (PMID 36703734, 2022).
atherosclerosis (continued). "In this study, we first explored the association of miR-145 expression with carotid artery intima-media thickness (CIMT) in patients with or without atherosclerosis cerebral infarction (ACI); then, we defined the role of miR-145 in CD40 expression both in vivo and in vitro." (PMID 27731400, 2016).